PTH (parathyroid hormone)
Diseases named in the same sentence as PTH in open-access papers (continued):
Sharing a sentence is not in itself a finding about the gene and the disease.
hyperparathyroidism (continued). "Among the 6 patients who did not undergo parathyroidectomy, only 1 did not have elevated calcium levels, but rather had high-normal calcium with elevated PTH and normal 25-hydroxy vitamin D, consistent with normocalcemic hyperparathyroidism." (PMID 32311048, 2020). "Despite its importance in physiology and its known role in diverse primary and secondary diseases (i.e., hyperparathyroidism and hypoparathyroidism), PTH has been far less studied in exercise endocrinology than calcium-phosphate metabolism." (PMID 32751307, 2020). "The wide dynamic range detection capability of READ to report significantly elevated PTH levels seen in patients suspected of hyperparathyroidism can be categorized as candidates for parathyroid surgery." (PMID 33139830, 2020). "At the time of current presentation, his hyperparathyroidism was well controlled with normal calcium and PTH levels." (PMID 32440625, 2020). "NT-N PTH represents 10% of total PTH values and up to 15% in patients with end-stage renal disease or a severe hyperparathyroidism or parathyroid cancers." (PMID 32148482, 2020). "Terms other than MeSH terms used were caffeine and parathyroid gland, caffeine, parathyroid hormone (PTH), parathyroid gland, hyperparathyroidism, parathyroid adenomas, diet, and parathyroid adenoma and caffeine and primary hyperparathyroidism." (PMID 32983662, 2020). "Hyperparathyroidism (HPT) is an endocrine disorder defined by a state of inappropriately increased levels of parathyroid hormone (PTH) activity from one or more parathyroid glands." (PMID 32148487, 2020). "Hyperparathyroidism (HPT) is the result of excessive secretion of parathyroid hormone (PTH) by the parathyroid glands, and three different forms are recognized: Primary, secondary, and tertiary." (PMID 33062583, 2020). "Patients with hyperparathyroidism will show increased synthesis of 1,25(OH)2D as a subsequent result of the elevation of PTH levels." (PMID 33015068, 2020). "Unfortunately, intact PTH assays also measure large circulating inactive C-terminal fragments of PTH potentially complicating the interpretation of hyperparathyroidism." (PMID 32582784, 2020). "Fb.V/TV of 1.08% (> 0.5%) and an increase of woven bone imply osteitis fibrosa, which suggested hyperparathyroidism due to higher serum levels of intact PTH; however, the patient’s serum levels of intact PTH were very low with post-PTX." (PMID 33180218, 2020). "Our recommendation for managing a patient with high PTH and normal calcium is continuous observation for the development of persistent hypercalcemic hyperparathyroidism." (PMID 32072184, 2020). "In patients with hyperparathyroidism secondary to end-stage renal disease, calcium levels decrease as a result of a rapid decrease in PTH after parathyroidectomy." (PMID 31966944, 2020). "Patients whose PTH levels were above the normal level were monitored because of decreased serum calcium levels and clinical signs of hyperparathyroidism." (PMID 31966944, 2020). "The incidence of hyperparathyroidism was more difficult to estimate because PTH levels are known to fluctuate overtime." (PMID 31151476, 2019). "Both symptomatic and asymptomatic patients were represented and patients with typical elevated serum calcium and PTH levels but also with normocalcemic hyperparathyroidism were included." (PMID 31367807, 2019). "Hyperparathyroidism due to benign parathyroid adenomas overproducing parathyroid hormone (PTH) is one of the most common endocrine disorders." (PMID 31750236, 2019). "It was mostly applied to monitor PTH in hyperparathyroidism patients with parathyroidectomy after PA." (PMID 30704522, 2019). "Hyperparathyroidism (HPT) is a state of overproduction of parathyroid hormone (PTH) due to over activity of one or more of the parathyroid glands." (PMID 30729318, 2019). "In severe hyperparathyroidism (SHPT) (PTH>600 pg/mL) patients, these levels were elevated regardless of serum albumin levels." (PMID 31839746, 2019).
hyperparathyroidism (continued). "Thirteen patients (86.7%) showed a hyperparathyroidism (median PTH level = 157 ng/l; interquartile range = 73–241 ng/l)." (PMID 30940121, 2019). "Although many patients with ESKD manifest hyperparathyroidism, the action of parathyroid hormone (PTH) is blunted in uremic status." (PMID 29772660, 2018). "While 12 of these patients showed hypocalcemic hyperparathyroidism, 38 patients displayed elevated PTH levels with normocalcemia." (PMID 29439698, 2018). "The analogy is with hyperparathyroidism in renal failure in which secondary activation of parathyroid hormone secretion can progress to autonomous hyperplasia and adenoma formation." (PMID 30289445, 2018). "Beyond PTH detrimental effects on the myocardium, several studies have also explored the impact of hyperparathyroidism on vascular homeostasis." (PMID 30662585, 2018). "Different pathologic conditions can affect serum PTH level resulting in hyperparathyroidism or hypoparathyroidism." (PMID 29794776, 2018). "In our case, nephrocalcinosis preceded the onset of hyperparathyroidism, while the level of PTH continued to rise after parathyroidectomy." (PMID 29983117, 2018). "Hyperparathyroidism is a condition which can be primary, secondary or tertiary and is characterized by increased calcium levels, low phosphate levels, and elevated parathyroid hormone (PTH) levels." (PMID 29581916, 2018). "But, no study has yet demonstrated the effects of excess continuous PTH exposure, such as that seen in hyperparathyroidism, for fracture healing." (PMID 30181648, 2018). "If excess PTH induces hypertension, a decline in blood pressure should follow ablation of parathyroid function in dialysis patients with severe hyperparathyroidism and hypertension." (PMID 29751781, 2018). "Parathyroid carcinoma is a rare neuroendocrine tumor associated with significantly increased parathyroid hormone (PTH) levels and hyperparathyroidism (HPT)." (PMID 30290620, 2018). "Several observational studies indicate that severe hyperparathyroidism may be associated with increased mortality in this population, presumably via a wide range of cardiovascular, metabolic, hematologic, and immunologic abnormalities induced by high concentrations of the uremic toxin PTH." (PMID 29107998, 2017). "Overproduction of PTH produces the pathophysiological disorder, hyperparathyroidism (HPT) which is characterized by hypercalcemia, hypercalciuria and increases in osteoclastic bone resorption." (PMID 29127344, 2017). "The clinical presentation of autoimmune hypocalciuric hypercalcaemia is identical to the presentation of the genetically determined forms, with moderate hyperparathyroidism, relative hypocalciuria, and inappropriate PTH." (PMID 28122587, 2017). "Considering iPTH as the reference and according to the area underthe ROC curve (AUC), 1-84 PTH had high value to predict hyperparathyroidism (AUC =0.926, P < 0.001)." (PMID 28975108, 2017). "Ionized calcium levels and parathyroid hormone levels were also elevated, and she was diagnosed with hyperparathyroidism." (PMID 28487796, 2017). "When comparing ERI with PTH <17.0 pmol/L (over-suppressed), 17.0–76.5 pmol/L (target range) and >76.5 pmol/L (hyperparathyroidism), ERI tended to be higher in the over suppressed group but there were no statistical significant differences." (PMID 29178879, 2017). "The present study aimed to first determine the agreement value between theiPTH and 1– 84 PTH measures in patients with hyperparathyroidism secondary to endstagerenal disease under chronic hemodialysis." (PMID 28975108, 2017). "The bone catabolic actions of parathyroid hormone (PTH) are seen in patients with hyperparathyroidism, or with infusion of PTH in rodents." (PMID 29127344, 2017). "The median serum PTH level was 38.1 pg/mL, and hypo- and hyperparathyroidism were present in 0.8% and 9.4% of the participants, respectively." (PMID 29149839, 2017).
hyperparathyroidism (continued). "One can acquire spuriously high PTH levels from grafted forearms, leading to the false diagnosis of recurrent hyperparathyroidism." (PMID 28645310, 2017). "The best cutoff point for 1-84 PTH to discriminate hyperparathyroidism from normal condition was 60 yielding a sensitivity of 92.3% and a specificity of 79.1%." (PMID 28975108, 2017). "At 1-year follow-up, 12 (19.4%) patients had residual/ recurrent hyperparathyroidism as evidenced by PTH levels persistently above the normal reference range." (PMID 28073343, 2017). "The case also underscores the importance of comprehensive surgery management and mindful interpretation of intraoperative PTH levels in the management of hyperparathyroidism." (PMID 28825015, 2017). "Serum intact Parathyroid Hormone (PTH) levels were 796 pg/ml (8–76 pg/ml) indicating hyperparathyroidism." (PMID 28732535, 2017). "The patient had a history of a remote parathyroidectomy for hyperparathyroidism; however, the parathyroid hormone (PTH) and the calcium levels were still mildly elevated." (PMID 29234569, 2017). "Considering iPTH as the reference and according to the area under the ROC curve, 1-84 PTH had high value to predict hyperparathyroidism (AUC = 0.926, P < 0.001)." (PMID 28975108, 2017). "In conclusion, our results demonstrate that MCP-1 is required for the effects on bone of hyperparathyroidism due to continuous infusion of PTH." (PMID 29127344, 2017). "PTH levels greater than 300 pg/ml indicate a potentially malignant disease with clinical manifestations of hyperparathyroidism appearing much before local invasion of tumor." (PMID 29354025, 2017). "Owing to the increased blood calcium level, hyperparathyroidism was suspected; however, the parathyroid hormone (PTH) level was found to be normal (PTH, 14 pg/mL; reference range, 12–88 pg/mL)." (PMID 29384906, 2017). "Contrastingly, continuous exposure to PTH, as observed in hyperparathyroidism, is catabolic to bone, increasing osteoclastogenesis through upregulation of RANKL and inhibition of osteoprotegerin expression." (PMID 27444010, 2016). "The development of the drug Cinacalcet to treat hyperparathyroidism was based on the ability of the CaSR to suppress parathyroid hormone release from the parathyroid gland." (PMID 27303307, 2016). "In different studies vitamin D has been associated with TDF-linked hyperparathyroidism emphasizing that both, TDF use and vitamin D status, influence in PTH values." (PMID 27699068, 2016). "In certain disease cases, such as hyperparathyroidism, it is necessary to control the function of PTH at the ligand level." (PMID 26932583, 2016). "Of note, ESRD was complicated by severe hyperparathyroidism for 4 years with PTH levels systematically above 2500 pg/mL and alkaline phosphatase levels ranging between 800 and 1500 IU/L." (PMID 27800197, 2016). "Hyperparathyroidism is a disease characterized by excessive secretion of parathyroid hormone, the hormone responsible for calcium and phosphate homeostasis in the body." (PMID 27277007, 2016). "Biochemical profiles showed that hyperphosphatemia (13.4 mg/dl, normal <4.6 mg/dl) with hyperparathyroidism (intact PTH level 85 pg/ml, normal <65 pg/ml)." (PMID 27462491, 2016). "Sustained exposure to high levels of parathyroid hormone (PTH), as observed in hyperparathyroidism, is catabolic to bone." (PMID 27444010, 2016). "Serum PTH levels, which correspond to the degree of hyperparathyroidism, were elevated by 3.4-fold in the CKD group, further confirming impaired renal function." (PMID 26955758, 2016). "Brown tumours of hyperparathyroidism are infrequent today due to improved medical technology that enables early diagnoses and correction of PTH levels." (PMID 26881146, 2016). "The link between hyperparathyroidism and hypertensive disorders is proposed to be related to the interaction of PTH with the renin-aldosterone system, the sympathetic nervous system, and the vascular endothelium." (PMID 27340578, 2016).
hyperparathyroidism (continued). "Calcium and phosphorus replenishment abolishes the feedback secondary hyperparathyroidism leading to fall in the serum PTH levels." (PMID 27158572, 2016). "Hyperparathyroidism, defined as serum PTH levels in the higher quartile (>44 pg/mL), was diagnosed in 56 out of 230 CHD patients (24.0%)." (PMID 26955207, 2016). "Concurrent deletion of the CaSR with parathyroid hormone gene corrected for the effects of hyperparathyroidism, hypercalcemia, hypophosphatemia, and whole-body growth retardation." (PMID 27303307, 2016). "There is also some evidence supporting the role of T-cells in PTH activity modulation in a mouse model of hyperparathyroidism." (PMID 27332712, 2016). "Parathyroid cysts are commonly manifested as hyperparathyroidism, and then changes in serum calcium and parathyroid hormone levels with disease progression." (PMID 27022378, 2016). "Significant pretransplant hyperparathyroidism and persistently high posttransplant PTH levels were observed in the hypercalcaemic population." (PMID 27493801, 2016). "All patients were cured of their hyperparathyroidism after this one exploration as demonstrated by normalization of their serum total calcium and PTH on the postoperative clinic visit 2 weeks later." (PMID 25629056, 2015). "Hyperparathyroidism (defined as serum PTH concentrations >6.5 pmol/L), hyperphosphataemia (defined as serum phosphate concentrations >1.50 mmol/L) and diabetes affected 25%, 9% and 15% of the study cohort, respectively." (PMID 25786244, 2015). "Since these patients were being treated with CH because of hyperparathyroidism, the impact of the potential unreliability of PTH assessment is great." (PMID 25384431, 2015). "In 4 cases, hyperparathyroidism was present but it seems unlikely that the degree of hypovitaminosis D with only a slight upregulation of PTH can explain the deep hypophosphatemia by itself." (PMID 25478250, 2014). "Such an incidental image should prompt biochemical work-up, including serum PTH assay (patient #7), as prolonged hyperparathyroidism will be detrimental in those elderly patients and requires medical or surgical treatment." (PMID 25177236, 2014). "Synergistic interaction between creatinine-corrected urinary concentrations of perchlorate, nitrate, and thiocyanate in influencing hyperparathyroidism (defined as parathyroid hormone >70 pg/mL) among the United States adults, NHANES 2005–2006." (PMID 25514572, 2014). "The aim of this exploratory study is to evaluate the association between urinary concentrations of perchlorate, nitrate, and thiocyanate and serum PTH level as well as the presence of hyperparathyroidism in U.S. adults." (PMID 25514572, 2014). "At our institution, medication for hyperparathyroidism is usually paused on the day of transplantation and PTH levels are regularly measured to observe their natural courses." (PMID 25606342, 2014). "Peculiarly, we observed an inverse relationship between 25(OH)D3 and PTH levels on one hand, and calcium concentrations on the other, both confirming the secondary origin of hyperparathyroidism." (PMID 24618074, 2014). "Regarding our results on the relationship between 25-OH-D and PTH, we found a remarkably high prevalence of hyperparathyroidism in our series of otherwise healthy adolescents." (PMID 24902694, 2014). "Among the 4,265 participants who formed our analysis sample, 449 (237 women and 212 men) had hyperparathyroidism (serum PTH >70 pg/mL)." (PMID 25514572, 2014). "Herein, I describe a patient who was thought to have recurrent hyperparathyroidism following a quadruple parathyroidectomy based solely on a high intact parathyroid hormone level." (PMID 23710381, 2013). "Generally, an increase in PTH would be accompanied by increased 1,25(OH)2D, as seen in hyperparathyroidism." (PMID 23741318, 2013). "The diagnosis of hypoparathyroidism due to maternal hyperparathyroidism was made in our patient upon evaluation of maternal PTH and Ca levels." (PMID 24072092, 2013).
hyperparathyroidism (continued). "Alternative definitions of hyperparathyroidism used values based on intact PTH (iPTH) with in one study the iPTH-level > 4.1 pmol/L, and in another study iPTH > 8.5 pmol/L together with 25(OH) vitamin D < 50 nmol/L, and s-Calcium ≤1.35 nmol/L." (PMID 24106456, 2013). "If MEN2 is suspected, further testing with a calcitonin, intact PTH, and calcium level is warranted to evaluate for medullary thyroid cancer and hyperparathyroidism." (PMID 23401807, 2013). "Yet, it is conceivable that parathyroid Klotho has a functional impact on vitamin D metabolism in PTH-KL−/− mice and that their elevated 1,25(OH)2D level contributes to normalizing PTH and counteracts development of hyperparathyroidism." (PMID 24348262, 2013). "The neurologist found a parathyroid hormone level of 901 pg/mL (upper limit of normal 65 pg/mL) and referred her for assessment of recurrent hyperparathyroidism." (PMID 23710381, 2013). "A reliable method to measure PTH is a key for detecting patients with hyperparathyroidism as well as subsequent monitoring of therapeutic interventions." (PMID 22792251, 2012). "For instance, lowering of sclerostin levels was demonstrated after injection of PTH and in patients with hyperparathyroidism." (PMID 23146624, 2012). "In 62 of the 100 patients, PTH levels were preoperatively determined, and 22.6 % of the patients had hyperparathyroidism." (PMID 22765843, 2012). "The putative mechanism for tendon rupture with renal failure and hyperparathyroidism includes parathyroid hormone-induced breakdown of bone matrix and increases bone resorption, thus weakening the bone-tendon interface." (PMID 23326731, 2012). "Despite resolution of the severe hyperparathyroidism over the infant’s first 3 months, her PTH continued to be in the high normal range despite increasing cholecalciferol dosing." (PMID 22620673, 2012). "Parathyroid hormone secretion is more disorderly in hyperparathyroidism, as is aldosterone secretion in primary and secondary hyperaldosteronism." (PMID 22363612, 2012). "Mean PTH at baseline was 31.04 (SD: 17.7) pg/mL; considering 65 pg/mL as a cut-off, 4/75 (5.3%) patients had hyperparathyroidism." (PMID 22333484, 2012). "Although the mean PTH level of the vitamin D insufficient group was below the cut-off value for hyperparathyroidism, it was significantly higher than that of the vitamin D sufficient group." (PMID 22155459, 2011). "The patient is an 83-year-old Caucasian woman who presented to an endocrinology clinic for evaluation of hyperparathyroidism, with an intact PTH of 462 pg/mL (normal range 14-72 pg/mL)." (PMID 22937291, 2011). "On the basis of the biochemical results (including serum calcium, phosphorous and intact parathyroid hormone levels) primary hyperparathyroidism was suspected and a brown tumor secondary to refractory hyperparathyroidism was diagnosed." (PMID 22204520, 2011). "High PTH levels, as in hyperparathyroidism, lead to renal phosphate wasting and hypophosphatemia, while low PTH levels, as in hypoparathyroidism, lead to increased renal phosphate reabsoption and hyperphosphatemia." (PMID 21858050, 2011). "Such patients are labelled as having “normocalcaemic hyperparathyroidism” in which calcium levels are normal but PTH is elevated." (PMID 22091440, 2011). "Severe hyperparathyroidism (defined as intact PTH >250 mg/dL) was present in 3 of 12 (25%) of the acute kidney injury subjects versus none of the subjects without acute kidney injury, although this result did not meet statistical significance." (PMID 21906363, 2011). "We present a narrative review of the literature relevant to PTH as an immune modulator and examine the effects of hyperparathyroidism on immune function in patients with CKD." (PMID 20886005, 2010). "Parathyroid apoplexy can lead to spontaneous remission of hyperparathyroidism, although in many cases the course of the phenomenon can be milder and can result only in asymptomatic reduction of calcium and PTH levels." (PMID 20184676, 2009).